TRDD1 (T cell receptor delta diversity 1)
Description:
D region of the variable domain of T cell receptor (TR) delta chain that participates in the antigen recognition. Gamma-delta TRs recognize a variety of self and foreign non-peptide antigens frequently expressed at the epithelial boundaries between the host and external environment, including endogenous lipids presented by MH-like protein CD1D and phosphoantigens presented by butyrophilin-like molecule BTN3A1. Upon antigen recognition induces rapid, innate-like immune responses involved in pathogen clearance and tissue repair. Binding of gamma-delta TR complex to antigen triggers phosphorylation of immunoreceptor tyrosine-based activation motifs (ITAMs) in the CD3 chains by the LCK and FYN kinases, allowing the recruitment, phosphorylation, and activation of ZAP70 that facilitates phosphorylation of the scaffolding proteins LCP2 and LAT. This lead to the formation of a supramolecular signalosome that recruits the phospholipase PLCG1, resulting in calcium mobilization and ERK activation, ultimately leading to T cell expansion and differentiation into effector cells. Gamma-delta TRs are produced through somatic rearrangement of a limited repertoire of variable (V), diversity (D), and joining (J) genes. The potential diversity of gamma-delta TRs is conferred by the unique ability to rearrange (D) genes in tandem and to utilize all three reading frames. The combinatorial diversity is considerably increased by the sequence exonuclease trimming and random nucleotide (N) region additions which occur during the V-(D)-J rearrangements.
Tractability: Antibody: UniProt places it where antibodies can reach, with high confidence; its Gene Ontology location is reachable by antibodies, with medium confidence.
Gene: T-cell receptor diversity (D) gene on chromosome 14 (22,438,547 to 22,438,554, forward strand). Ensembl gene ENSG00000223997.
Subcellular location: Cell membrane
Gene Ontology:
Cellular component: plasma membrane